CCL2 (C-C motif chemokine ligand 2)
Diseases named in the same sentence as CCL2 in open-access papers (continued):
Sharing a sentence is not in itself a finding about the gene and the disease.
tumor (continued). "Due to the tumor immunosurveillance function of microglia in brain tissue, we then detected the expression of cytokine IL6 and chemokine CCL2 in BC-BM brain tissue." (PMID 40444044, 2025). "CCL2, a downstream molecule of IL-33, recruits Tregs via the NF-κB/CCL2 pathway, promoting EMT and thereby facilitating tumor development and metastasis." (PMID 40134607, 2025). "Cytokines including CCL-2, IL-6, IL-8, IL-10, IL-13, and TNF-α show tumor-specific secretion profiles, with experimental evidence demonstrating TIC-derived cytokines mediate immune evasion through recruitment and activation of MDSCs and TAMs." (PMID 40777043, 2025). "Tumors attract IMs by secreting monocyte chemoattractant protein-1 (MCP-1 or CCL2), which can promote tumor cell proliferation, migration, and survival." (PMID 40242762, 2025). "Importantly, though, with our PCLS and in situ data, we cannot distinguish whether the ZEB1-dependent CTL abundance (in situ) and the CCR2/CCR4-dependent tumor control (PCLS) are regulated by a direct recruitment of CD8 + T cells by CCL2 and/or CCL22 or other alternative mechanisms." (PMID 40595293, 2025). "In ACC, a key signaling axis involves tumor-derived CCL2 recruiting CCR2+ TAMs, which in turn secrete GDNF to drive tumor cell proliferation via the RET pathway." (PMID 41164198, 2025). "We also identified several pivotal contributors to the pro-tumor microenvironment, notably OMD+ fibroblast and CCL2+ macrophage." (PMID 40092486, 2025). "LAMs are myeloid-lineage cells derived from circulating monocytes, which are recruited into the LME by tumor, and EBV-derived factors such as CCL2, colony-stimulating factor 1 (CSF-1), and inflammatory cytokines." (PMID 41303704, 2025). "Particularly important, in the experiment of the allogeneic intracranial orthotopic GBM model, deguelin showed the ability to inhibit tumor growth and inhibit GBM angiogenesis by inhibiting the CCL2/NF-κB pathway in vivo." (PMID 40672375, 2025). "Following RT, a range of immunosuppressive cytokines, such as CSF‐1, CCL2, and CXCL12, are released, which promote the recruitment of Treg cells, MDSCs, TAMs, and other immunosuppressive cells into the tumor tissue." (PMID 40900811, 2025). "During carcinogenesis, malignant cells release CCL2 to recruit CCR2-positive classical monocytes and Mo-MDSCs to promote tumor growth and progression." (PMID 40427136, 2025). "Both CCL2 and CCL7 serve as ligands for the chemokine receptor CCR2 17, which was found to be overexpressed in TRPC tumor infiltrates." (PMID 40661379, 2025). "CCL2 has the ability to draw CCR2-positive monocytes into the tumor microenvironment, prompting their differentiation into TAMs, ultimately fostering tumor growth and metastatic processes." (PMID 41394878, 2025). "The EMT program further amplifies CCL2 production, fostering continuous macrophage influx and establishing a self-reinforcing TAM–tumor interaction that accelerates migration, invasion, and metastasis." (PMID 40963633, 2025). "Further inspection of the human scRNA-Seq dataset identified a population of tumor cells expressing high levels of TGF-β1 and CCL2." (PMID 40794443, 2025). "Silibinin weakens tumor-stroma interactions by downregulating exosomal miR-155 and CAF-derived CCL2, breaking the CSC-stromal feedback loop." (PMID 40650040, 2025). "CCL2 and its receptor CCR2 promote tumor cell proliferation and metastasis by attracting monocytes and macrophages in the tumor microenvironment." (PMID 40918470, 2025). "In clinical trials, inhibitory therapeutic targeting of the CCL2 and CCL22 axes were often unfavorable for patients, reinforcing an overall anti-tumorigenic effect of CCL2 and CCL22 at least in certain tumor settings." (PMID 40595293, 2025). "The attraction of MCs to a tumor requires the action of different chemokines produced by the tumor cells such as the stem cell factor (SCF), CXCL2, CCL2, CCL5, CCL11, CXCL12, CCL15, IL-3, and IL-33." (PMID 41465542, 2025).
tumor (continued). "This shift in population activates the HMG-B1/NF-κB signaling pathway in macrophages, leading to secretion of the C-C motif chemokine ligand 2 (CCL2) and tumor necrosis factor-α (TNF-α) chemokines, which in turn promotes MDSC infiltration and tumor metastasis." (PMID 40539068, 2025). "The CCL2/CCR2 axis recruits monocytes to the OC TME, where CCL2 drives their M2-like TAM differentiation, promoting tumor growth and chemoresistance." (PMID 41280929, 2025). "CCL2 facilitates the recruitment of MDSCs to tumors and promotes immunosuppression in a CCR2-dependent manner, ultimately contributing to tumor growth." (PMID 41368628, 2025). "Here, we confirm that CCL2 secreted from PDPN(+) CAFs acts as a powerful mediator between CAFs and ECs to facilitate tumor angiogenesis." (PMID 39764562, 2025). "Tumor cells and CAFs recruit macrophages into the TME by secreting CCL2, and these macrophages are usually M2type with immunosuppressive function." (PMID 41376630, 2025). "As mentioned in the previous section, targeting the CCR2/CCL2 signalling axis as well as VEGFR2 can reduce macrophage infiltration and suppress tumour growth in murine models." (PMID 40385641, 2025). "Breast cancer and stromal cells in TME cells secrete chemokines CCL2, CCL5 (RANTES), CCL20, CCL22, and CXCL12 which, by binding to the corresponding receptors, induce Treg homing to tumor tissue." (PMID 40940764, 2025). "Chemokines including CXCL5/CXCR2 are essential for MDSC recruitment in 4T1 BALB/c murine tumor models, while CCL1, CCL2, CCL5, GM-CSF, and G-CSF facilitate MDSC expansion and aggregation in the tumor milieu." (PMID 40909271, 2025). "Studies have shown that CAFs upregulate levels of C-C motif chemokine ligands such as CCL2, CCL5, and CCL20 to coordinate activation of HCC cell ERK/PKM2 and TGF-β pathways to enhance tumor metastasis phenotype and regulate tumor metabolism." (PMID 40028341, 2025). "Several CAF-derived chemokines such as CCL2, CCL26, IL6, CXCL1, and CXCL8 mediate tumor progression, angiogenesis, and drug resistance, suggesting that tumor–CAF crosstalk is a bidirectional, dynamic, and adaptive process." (PMID 40447617, 2025). "This activation triggers upregulation of chemokine (C-C motif) ligand 2 (CCL2), which facilitates the directed migration of GAMs toward the tumor site." (PMID 41479886, 2025). "The role of CCL2, HAVCR2, and BIRC5 in immune modulation and tumour progression present potential therapeutic targets." (PMID 40683913, 2025). "In CRC, HCAR1 signaling promotes the secretion of chemokines CCL2 and CCL7 by tumor cells, which in turn recruit CCR2+ PMN-MDSCs." (PMID 41152975, 2025). "Subsequently, we examined the mRNA levels of CCL5, CD274, CXCL10, CXCL11, and CCL2 in MDA‐MB‐231 and 4T1 cells and tumor tissues." (PMID 39585774, 2025). "The CCL chemokines CCL2, CCL7, CCL8, and CCL12 are known ligands for CCR2 expressed on circulating monocytes and facilitate their recruitment into the tumor microenvironment." (PMID 40867322, 2025). "Targeting monocyte recruitment pathways, such as C-C motif ligand 2/C-C motif chemokine receptor 2 (CCL2/CCR2), has shown promise in reducing tumor infiltration by monocyte-derived macrophages." (PMID 40098971, 2025). "CCL2, in particular, mediates the recruitment of CCR2-expressing monocytes from the bloodstream into the tumor bed, where they subsequently mature into TAMs." (PMID 41058699, 2025). "TNF-α, a key pro-inflammatory cytokine in tumors, is constitutively overexpressed via its receptor on tumor cells, correlating with sustained NF-κB activation and elevated MCP-1/CCL2 expression." (PMID 41341593, 2025). "The expression of chemokines, such as CCL2, CCL3 and CCL5, in the tumor microenvironment in both human and murine models are associated with enhanced recruitment of myeloid-derived cells including macrophages." (PMID 39566333, 2025).
tumor (continued). "Conversely, in lung cancer, NF-κB activation upregulates chemokines such as CCL2, CCL5, and CXCL10, facilitating effector T cell infiltration and enhancing anti-tumor immunity." (PMID 41035656, 2025). "Specifically, lactate enhances the production of C-C motif chemokine ligand 2 (CCL2) and C-C motif chemokine ligand 7 (CCL7) by tumor cells in CRC, thereby driving the recruitment of CCR2+ polymorphonuclear MDSCs (PMN-MDSCs)." (PMID 41152975, 2025). "Upon being recruited to inflammatory tumor tissues in response to chemokines like CCL2, CCL5, CXCL8, and CXCL12, MDSCs rapidly produce immunosuppressive mediators, including ARG1, NO, TGF-β, and IL-10, which further impair anti-tumor immunity." (PMID 40563367, 2025). "In particular, CCL2 binds to its receptor CCR2 and induces the expression of EMT-TFs Snail1 and Twist1 in cancer cells, producing morphological changes to support tumour cell migration toward SCs." (PMID 40037534, 2025). "Recruited by tumour-derived chemokines such as CCL2, CCL5, and CCL8, TAMs are reprogrammed to enhance EMT, tumour motility, and metastasis, while hampering T-cell infiltration." (PMID 40361472, 2025). "Their functional maturation is promoted by cytokines such as IL4, IL6, IL13, and TNF, while mobilization into the tumor niche is orchestrated by chemoattractants including IL8, CCL2, and CXCL12." (PMID 41155172, 2025). "For instance, tumour cells with high FAT2 expression have been reported to upregulate several chemokines that influence immune cell behaviour, including CCL2, CCL3, CCL4, CCL19, CXCL10, and CXCL11." (PMID 40361472, 2025). "EVs derived from GBM induce TAM secretion of CCL2, IL-6 and VEGF, which promote monocyte recruitment, tumor invasion, and angiogenesis, respectively." (PMID 40386422, 2025). "Pathway analyses indicated a difference in inflammatory response between the two primary tumours, with upregulation of OAS2, CCL2, and AKAP13 in Patient 1 compared to Patient 2 across all cell populations." (PMID 40438247, 2025). "In tumors, cancer cell‐derived CCL2 and CCL5 usually contribute to the recruitment of MDSCs, TAMs, and Tregs to the tumor niche." (PMID 40105652, 2025). "One recent study pointed out that LDHA upregulated C-C motif chemokine ligand 2 (CCL2) and CCL7 through the ERK-YAP-STAT3 signaling axis to recruit macrophages into the tumor microenvironment." (PMID 40093910, 2025). "Our findings suggested that CCL2 and CCL22 from ZEB1-expressing alveolar macrophages increase CTL abundance to limit metastatic lung colonization of KPC tumor cells." (PMID 40595293, 2025). "M2-TAMs further secrete chemotactic factors including CCL2, CCL5, and macrophage colony-stimulating factor-1 (CSF-1), thereby contributing to immunosuppression and establishing a supportive niche for tumor angiogenesis, metastasis, and invasion." (PMID 40936918, 2025). "These macrophages are attracted to the tumor microenvironment by chemotactic signals, including colony‐stimulating factor‐1 (CSF‐1), VEGF‐A, and chemokine (C‐C motif) ligand 2 (CCL2)." (PMID 40944395, 2025). "In the tumor microenvironment, however, both IL-6 and CCL2 predominantly support M2-like TAM polarization, thereby fostering angiogenesis, immune suppression, and tumor progression." (PMID 41310829, 2025). "Genes implicated in embryonic and organ development, including SHH, NEUROG3, and MAFA, were downregulated, while immune-related genes like CCL2 and HAVCR2 were upregulated, suggesting immune modulation and alterations within the tumour microenvironment." (PMID 40683913, 2025). "Targeting key inflammatory mediators—such as the CCL2/CCR2 axis, CSF1R, or the IL-1β signaling pathway—has demonstrated promising anti-tumor effects in preclinical models." (PMID 40881678, 2025).
tumor (continued). "The mechanism involves c-Jun/AP-1 mediating TLR7/8 signaling in IFN-I-primed DCs, upregulating the pDC-recruiting chemokine CCL2 and the anti-angiogenic cytokine interleukin-12, which suppresses VEGF-A production leading to tumor necrosis and regression." (PMID 39849091, 2025). "CCL2, or monocyte chemoattractant protein-1 (MCP-1), is synthesized by various cell types, including tumor and endothelial cells." (PMID 40909948, 2025). "In pancreatic cancer models, BET inhibition reduces HO-1 expression in macrophages and suppresses tumor-promoting cytokines such as IL-6, CCL2, and GM-CSF, demonstrating a direct link between BET activity and the immunosuppressive tumor microenvironment." (PMID 41583469, 2025). "β-catenin activation in tumor cells upregulates EMT-promoting transcription factors such as ZEB1 and Snail, as well as chemokines including CCL2 and CCL3, which recruit monocytes and polarize them into M2-like TAMs." (PMID 40963633, 2025). "M-MDSCs are mainly chemotactic through the binding of the CCR2 receptor with chemokines such as CCL2, CCL8, and CCL12, and they also play a variety of immunosuppressive and tumor-promoting roles in the TME." (PMID 40179015, 2025). "Initial candidates for overexpression have been the chemokine receptors CCR2 and CXCR2 (receptors for CCL2 and CXCL8/IL-8, respectively) for CAR and transgenic TCR T cells, as well as TILs, which revealed increased tumor infiltration in several models." (PMID 41181132, 2025). "In breast fibroblasts, TGF-β signaling inhibits CCL2 expression and negatively regulates TAM recruitment and tumor metastasis." (PMID 41341593, 2025). "These YGP-activated monocytes exert direct cytotoxicity against tumor cells in vitro, and systemic YGP treatment increases the levels of inflammatory mediators such as TNF-α, M-CSF, and CCL2 in the lungs." (PMID 41163402, 2025). "Immunochemistry of tumor tissues harvested earlier also confirmed that the group with PDPN(+) CAFs expressed higher levels of PDPN, CCL2, and p‐AKT in the tumor stroma compared to the PDPN(−) CAFs group and NC group." (PMID 39764562, 2025). "We reported a significant, higher than in 4T1 tumor-bearing mice, 2’3’-cGAMP-induced increase in CXCL10, CCL2, CCL4, TNF-α, IFN-α and IFN-β concentrations." (PMID 39857957, 2025). "Conversely, EMT-transformed tumor cells reinforce TAM recruitment and M2 polarization through immunomodulatory factors such as CCL2 and ZEB1, thereby establishing a bidirectional interplay that fuels tumor progression." (PMID 40304000, 2025). "Tumor cells secrete chemoattractants such as CCL2 and VEGF to recruit monocytes from the blood into the tumor microenvironment." (PMID 40787471, 2025). "We engineered armed Muc16/CA-125-directed CAR-T cells with cognate receptors for CCL2 and CCL4 and showed significant in vitro and in vivo tumor-directed trafficking." (PMID 41424784, 2025). "Produced by both tumor and stromal cells within the tumor microenvironment (TME), CCL2 acts as a potent chemoattractant for monocytes and macrophages." (PMID 40940890, 2025). "Numerous studies revealed that chemokines such as CXCL1, CXCL2, IL-8 (CXCL8), CXCL5, CXCL12, CCL2, and MIP-1α (CCL3) promote the infiltration of neutrophil to the tumoural microenvironment." (PMID 40852716, 2025). "Thirdly, TAMs inhibit the recruitment of T cells to tumor sites by producing peroxynitrites and nitrifying CCL2 and CCL5, thereby preventing chemotaxis of CAR-T and other T cells to the tumor, reducing their effectiveness." (PMID 39136031, 2024). "The knockdown of CCL2 via viral transfection attenuated AAE’s effects on NK cell infiltration and tumor growth inhibition, further validating these findings." (PMID 39206194, 2024).
tumor (continued). "CCL9 and CCL2 play a role in mobilizing PMN-MDSCs from the spleen to peripheral blood, thereby facilitating tumor initiation and growth." (PMID 39206194, 2024). "Under the combined influence of hypoxia and cytokines, such as CCL2, CCL5 and CSF1–-produced by tumor cells, fibroblasts, endothelial cells, or TAMs themselves, macrophages will be largely recruited to hypoxic tumor compartments." (PMID 39175095, 2024). "Chemokines such as CCL2 and CCL5 attract immune cells to the tumor site, facilitating a robust immune attack, critical for combating tumor heterogeneity and adaptive resistance mechanisms." (PMID 39103972, 2024). "The chemotactic (C-C Motif) chemokine ligand 2, CCL2, released by tumor cells recruited monocytes into the TME." (PMID 39459945, 2024). "Other pharmaceutical agents, including the CCL2 inhibitor bindarit, anti-CCL2 mAb carlumab, CSF1 inhibitor GW2580, and dequalinium-14, CD40 antagonist CP-870,893, have also shown anti-tumor effects by reducing macrophage infiltration." (PMID 39146202, 2024). "A substantial body of research substantiates that CC chemokines (e.g., CCL2, CCL5) and CXC chemokines (e.g., CXCL1, CXCL2, CXCL5) recruit diverse immune cells, such as CCR2+ monocytes and CXCR2+ neutrophils, to tumor sites." (PMID 39206194, 2024). "CCL2 contributes to TAM survival during inflammation, which is crucial for maintaining a supportive microenvironment for tumor growth." (PMID 39201480, 2024). "Various stimulatory factors released by tumor cells, such as TNF-α, IL-1β, etc., can activate the NF-κB signaling pathway, thus promoting the expression of CCL2." (PMID 39065562, 2024). "Chemokines, such as CCL2, CCL5, and CXCL12, are vital for the recruitment of monocytes into tumor tissues." (PMID 39516356, 2024). "The expression of angiogenic factors (e.g., Angiopoetinn-1, FGF acidic), chemokines (e.g., CCL2, CXCL13), and inflammatory cytokines (e.g., IL-6, IL-1 beta), which were elevated in serum from tumor embedded mice, was suppressed by Pn-21Ab administration." (PMID 39334860, 2024). "Since CCL2, as a secreted factor, plays a role in immune cell chemotaxis through the CCR2 receptor, we extracted the supernatants of cultured tumor cells for ELISA." (PMID 38216673, 2024). "By up-regulating factors such as arginase 1 (ARG1) and CCL2, TGF-β promotes tumor growth and the potential for metastasis by facilitating the conversion of N1-type TANs to N2-type." (PMID 39456636, 2024). "Instead, it results in increased expression of CCL2 in pericytes, which subsequently activates MEK1-ERK1/2-ROCK2 signaling in tumor cells, ultimately leading to accelerated tumor growth." (PMID 38528180, 2024). "Remarkably, the supernatant of tumor monocytes was able to induce a higher expression of CRC EGC marker genes (Lcn2, Timp1, Ccl2, and Il6) compared to control BM-derived monocytes in an IL-1R-dependent manner." (PMID 39030280, 2024). "CCR2 is the cognate receptor to the CC-chemokine, monocyte chemotactic protein 1 (MCP-1), also known as CCL2, which is widely secreted by hepatocytes, Kupffer cells, hepatic stellate cells, liver sinusoidal endothelial cells and HCC tumour cells." (PMID 39684877, 2024). "PNT can also reduce the efficiency of MHC I binding with peptides on the membrane of cancer cells, nitrating CCL2, STAT1, and Lymphocyte cell-specific protein-tyrosine kinase (LCK) to inhibit anti-tumor immunity." (PMID 38720342, 2024). "Juzentaihoto treatment as well as the combination treatment (but not Gemcitabine treatment alone) showed a significant increase of the macrophage chemoattractant chemokines CCL2/MCP-1, CCL20/MIP3α, and CXCL2/MIP-2 in the supernatant of tumor cells." (PMID 39723364, 2024). "Conditioned media from MSCs are rich in chemokine ligand 2 (CCL2)/monocyte chemoattractant protein-1 (MCP-1), matrix metalloproteinases (MMPs), and ILs, which promote tumor aggressiveness and chemoresistance in BC cells." (PMID 39624211, 2024).